CXCR4 (C-X-C motif chemokine receptor 4)
Diseases named in the same sentence as CXCR4 in open-access papers (continued):
Sharing a sentence is not in itself a finding about the gene and the disease.
breast carcinoma (continued). "Additional studies show that combined CCR7 and CXCR4 expression is also correlated with lymph nodes metastasis in breast cancer, gastric cancer, cervical cancer, and melanoma." (PMID 24259307, 2013). "CXCR4 has also been found to be a prognostic marker in various types of cancer, including acute myeloid leukemia, breast cancer, and prostate cancer." (PMID 23936528, 2013). "A functional hypoxic response element has been found on IL-19 promoter, and hypoxia induces IL-19 expression consistent with the increased expression of CXCR4 in breast cancer cell lines." (PMID 23710200, 2013). "Receptor CXCR4 was overexpressed in HER2-negative breast cancer patients and was correlated with disease-free survival." (PMID 24649267, 2013). "Concurrently, invasive late stage lesions mainly contained CXCR4++ cells, which is in line with the clinically reported higher expression of CXCR4 in more invasive types of breast cancer." (PMID 23326303, 2013). "It would be interesting to explore the relationship between HER2 expression and the hypoxia/IL-19/CXCR4 pathway in the progression of breast cancer." (PMID 23710200, 2013). "Analysis of breast cancer and lymph nodes tissue microarrays of the same patients revealed that CXCR4 and CCR7 together with their ligands as well as EGFR were significantly higher expressed in tumor cells with lymph node metastasis." (PMID 23667660, 2013). "Studies show that metastatic breast cancers selectively express CXCR4 and migrate to organs that express high levels of its respective ligand CXCL12, also known as SDF-1." (PMID 24259307, 2013). "In vivo, neutralizing CXCR4/SDF-1 signaling axis significantly impaired breast cancer cell extravasation and propagation." (PMID 23967403, 2013). "Chemokines seem to be important in the brain metastasis formation of breast cancer cells as well, since the CXCR4/SDF1 signaling pathway was shown to have a decisive role in the migration of breast cancer cells through brain endothelial monolayers." (PMID 23344048, 2013). "Data of Cabioglu and colleagues provided evidence that CCR7 together with CXCR4 are valid biomarkers predicting axillary lymph node metastasis in T1 breast cancer." (PMID 23667660, 2013). "Several types of cancer over express CXCR-4 including breast cancer tissue but the normal breast tissue has low expression." (PMID 26237142, 2013). "As demonstrated in our study, after breast cancer patients were treated with neo-adjuvant systemic therapy, decreased expressions of C-erbB2, ER-α and CXCR4 were observed." (PMID 23046610, 2012). "Using in vitro and intravital observation techniques, we were able to demonstrate that CXCR4 plays an important role in guiding breast cancer cells to target organs, such as liver, due to integrin-adhesion dependent activation." (PMID 22253872, 2012). "Inhibition of the pathway of CXCR4/CXCL12 would decrease breast cancer cells migration as well as vascular permeability." (PMID 23443093, 2012). "In the MDA-MB-231 breast cancer cell line, Altenburg and Siddiqui, 2009 showed that n − 3 PUFAs exposure resulted in a decreased level of the chemokine receptor CXCR4, which requires intact lipid rafts for signaling." (PMID 22811918, 2012). "In particular, the chemokine/receptor pair SDF-1/CXCR4 has been involved in the regulation of metastatic potential of neoplastic cells, including breast cancer." (PMID 22417013, 2012). "The expression of CXCR4 in each culture was verified by IF staining, confirming the immunopositivity of mammary carcinoma primary cells, as in the tissue of origin." (PMID 22417013, 2012). "There is compelling evidences that chemokine receptors, for example, CXCR4, mediate breast cancer metastasis." (PMID 22505933, 2012). "Study in metastatic breast cancer revealed that the breast cancer cells high expression of CXCR4 metastasized to the corresponding target organs with high expression of CXCL12, such as lymph nodes and bone marrow." (PMID 22537906, 2012).
breast carcinoma (continued). "Nuclear CXCR4 expression has been described in breast cancer and lung cancer, which suggests that nuclear CXCR4 staining predicts lymphatic invasion and lymph node metastasis of cancer." (PMID 23039915, 2012). "The chemokine CXCL12 and its receptor CXCR4 play important roles in the colonization of human breast cancer cells to their metastatic target organs." (PMID 22253872, 2012). "Inhibiting CXCR4 expression in breast cancer cells, using different strategies (e.g., siRNA silencing, phenotypic CXCR4 knockout, peptide inhibitor of protein kinease-α), also suppressed breast cancer metastasis." (PMID 22842551, 2012). "Exposure of MDA-MB-231 breast cancer cells to n − 3 PUFAs results in decreased surface levels of CXCR4 in a time- and dose-dependent manner." (PMID 22811918, 2012). "The aim of this study was the immunohistochemical defininition of the expression profile of CXCR4 in primary and metastatic feline mammary carcinomas and the evaluation of the role of SDF-1 in feline mammary tumour cell proliferation." (PMID 22417013, 2012). "In vivo studies on breast cancer demonstrated that treatment with miRNA or antibodies against CXCR4 impaired migration and the development of murine lung metastases." (PMID 22518090, 2012). "Previously, both CXCR4 and c-Met were shown to be upregulated by hypoxia in glioma cells and breast cancer cells." (PMID 22242160, 2012). "In vivo, neutralizing the interactions of CXCL12/CXCR4 significantly impairs metastasis of breast cancer cells to regional lymph nodes and lung." (PMID 23905066, 2012). "It has been reported that CXCR4 can be up-regulated through NF-kB in prostate and breast carcinomas." (PMID 21743395, 2012). "In veterinary oncology, Oonuma and collaborators found a similar response in vitro using established feline mammary carcinoma cell lines incubated with CXCR4 antagonists." (PMID 22417013, 2012). "It has been demonstrated that NFκB promotes breast cancer cell migration and metastasis by inducing the expression of the chemokine receptor CXCR4." (PMID 23905066, 2012). "It has been shown that HER2- signalling in breast cancer enhances the expression of CXCR4, which is required for HER2-mediated invasion." (PMID 23082154, 2012). "Over-expression of CXCR4 is considered a key regulatory step in several human malignancies included breast cancer, resulting in a poor prognosis." (PMID 22417013, 2012). "Recently, a novel role of CXCR4 has emerged that reveals CXCR4 mediates resistance to endocrine therapy in human breast cancer and chemotherapy in CRC." (PMID 23071744, 2012). "In breast cancer cells, CXCR4 is a major chemokine receptor with possible but undefined roles in metastatic cell diffusion and homing to secondary sites." (PMID 22242160, 2012). "The results from this study showed that enhanced CXCR4 signaling is sufficient to drive ERα-positive breast cancers to a metastatic and endocrine-therapy-resistant phenotype via increases in MAPK signaling." (PMID 22295247, 2012). "The role of CXCR4 in the metastatic cascade of breast cancer and also its ability to predictpatient survival have been intensively studied." (PMID 22253872, 2012). "Recent evidence suggests that the SDF-1/CXCR4 pathway is involved in local invasion and metastasis of many cancers, including breast cancer, gastric cancer and ovarian cancer." (PMID 22200669, 2012). "The chemokine CXCL12/SDF-1 and its G-protein-coupled receptor CXCR4-mediated signaling pathways play important roles in the migration and invasion of breast cancer cells." (PMID 22295247, 2012). "In breast cancer cells, signalling through CXCR4 or CCR7 mediates actin polymerization and pseudopodia formation and subsequently induces chemotactic and invasive responses." (PMID 23905066, 2012). "Overexpression of the chemokine receptor CXCR4 was originally detected in human breast cancer cells, malignant breast tumors and metastases." (PMID 22842551, 2012).
breast carcinoma (continued). "With the increase in the development of novel therapeutic agents feline mammary carcinomas can provide a useful model to test new drugs, as far as efficacy and toxicity, including novel CXCR4 antagonists." (PMID 22417013, 2012). "A prior study revealed that NF-κB promoted breast cancer migration and invasion by directly upregulating CXCR4 expression." (PMID 22200669, 2012). "After transfection with PKCζ-siRNA, the phosphorylation of PKCζ and CXCR4 was abrogated in breast cancer cells." (PMID 22242160, 2012). "To do this, we determined the expression of HGF, c-Met and CXCR4 in breast cancer tissues by immunohistochemistry using corresponding antibodies, which revealed positive immunostaining of HGF, c-Met or CXCR4 in 197 cases of invasive breast carcinoma." (PMID 22242160, 2012). "Six primary, fibroblast-free primary cultures were obtained from fresh feline mammary carcinomas and characterized by immunofluorescence for CXCR4 and malignant mammary cell marker expression." (PMID 22417013, 2012). "To evaluate the specificity of CXCR4 expression in mammary carcinomas and metastasis, we analyzed the level of CXCR4 immunopositivity in normal mammary tissues and benign lesions (1 basaloid adenoma and 1 complex adenoma)." (PMID 22417013, 2012). "In vitro, 5 out of 6 analyzed primary cultures of mammary carcinoma cells showed significant increased cell proliferation in response to CXCR4 activation by nanomolar concentrations of SDF-1." (PMID 22417013, 2012). "In the present study we demonstrated, for the first time, a high CXCR4 expression in several feline high grade mammary carcinoma, evaluated at protein level by immunohistochemistry." (PMID 22417013, 2012). "CXCR4 is a critical factor in the invasiveness and proliferation of breast cancer cells and plays a pivotal role for the growth of malignant neuronal and glial tumors." (PMID 22693649, 2012). "CXCR4 expression in breast cancer cells has been shown to increase metastasis by homing of tumor cells to sites of increased CXCL12 expression, such as the lymph nodes." (PMID 22314082, 2012). "To further examine the effects of HGF-induced CXCR4 expression via PKCζ on breast cancer invasion and metastasis in vivo, we inoculated the mammary fat pads of athymic nude mice with MDA-MB-436 cells." (PMID 22242160, 2012). "Taken together, the results of our study provided new insights to molecular regulation of CXCR4 and to certain distinct regulatory molecules that can be targeted to modulate the CXCR4 signaling in breast cancer." (PMID 22242160, 2012). "Breast cancer cells expressing CXCR4 in circulation effectively enter the bone marrow niche due to enhanced expression of CXCL12 in this environment." (PMID 22505933, 2012). "The present study addressed the molecular aspects of the regulation of CXCR4 in human breast cancer cells." (PMID 22242160, 2012). "CXCL12 binds to the G protein-coupled receptor CXCR4, which is often overexpressed in breast cancer and has been correlated with poor clinical outcome." (PMID 22314082, 2012). "CXCR4 antagonist can downregulate its expression in breast cancer cells, thus repressing metastasis in animal models." (PMID 23181100, 2012). "CXCR4-directed antibodies suppressed lymph node metastasis in experimental breast cancer and suppressed tumor growth and impaired the development of tumor endothelium in experimental models of colon and pancreatic cancer." (PMID 22433180, 2012). "Both investigated breast cancer cell lines expressed functionally active CXCR4 at their surfaces and their in vivo potential for chemotactic extravasation rates into the liver parenchyma was comparable." (PMID 22253872, 2012). "Focused settings, such as relapsed glioblastoma, neoadjuvant colorectal and breast cancer, and advanced prostate cancer would be ideal for evaluating CXCR4-inhibiting agents in the development and progression of metastases." (PMID 22399057, 2012).
breast carcinoma (continued). "To demonstrate that SDF-1 effects occurred through CXCR4 expressed in feline mammary carcinoma cells, we exposed cells to the CXCR4 antagonist AMD3100." (PMID 22417013, 2012). "A recent report has highlighted the role of CXCR4 as a prognostic marker in various types of cancer, including leukemia and breast cancer." (PMID 23158844, 2012). "HGF is able to induce CXCR4 expression and contributes to tumor cell invasiveness in breast carcinoma." (PMID 22242160, 2012). "The NF-κB binding site has also been identified in the proximal region of the CXCR4 promoter and is postulated to play a role in CXCR4 expression in human breast cancer cells." (PMID 22200669, 2012). "Breast cancer cells specifically express functionally active CXCR4 and CCR7, which can trigger actin polymerization, pseudopodia formation and directional movements." (PMID 22253872, 2012). "The aim of the present study was to investigate, by immunohistochemistry, the levels of CXCR4 expression in feline mammary tumours and metastases, and the proliferative activity induced by SDF-1 on feline carcinoma primary cultures." (PMID 22417013, 2012). "When the c-Met+ and CXCR4+ cell counts in breast cancer were calculated according to the clinicopathology of these patients, the numbers of HGF+, c-Met+ or CXCR4+ cells increased along with the histopathological grading of the tumor (P<0.001)." (PMID 22242160, 2012). "Here, besides the expression of CXCR4 in feline mammary tumours, we also investigated the functional role of this receptor in mediating proliferative signals." (PMID 22417013, 2012). "Breast cancer cells from primary tumors over-expressing CXCR4 are attracted to CXCL12 expressing cells in the lung, lymph nodes, liver or bones, which leads to the metastasis of detached tumor cells." (PMID 22220212, 2011). "CXCR4 is the receptor for the chemokine SDF-1, is important in the metastatic potential of estrogen receptor positive ovarian and breast cancer and is linked to poor prognosis in a variety of tumor types and leukemias." (PMID 21261996, 2011). "First, we evaluated the regulation of the CXCR4 gene by DNA methylation in breast cancer cell lines." (PMID 22220212, 2011). "This group analyzed the association of locally advanced breast cancer (stages IIB or III of the TNM staging system) and CXCR4 expression after neoadjuvant therapy." (PMID 22220212, 2011). "As CXCR4 expression has been correlated with poor overall survival rate in patients with breast cancer, and colorectal cancer, CXCR4 has been considered as a potential therapeutic target for inhibiting cancer metastasis." (PMID 21880153, 2011). "To confirm the epigenetic transcriptional silencing of CXCR4 in breast cancer, we treated the MDA-MB-435 cell line with the demethylating agent 5-aza-2′-deoxycytidine (5-aza-CdR)." (PMID 22220212, 2011). "The positive regulation of CXCL12 and CXCR4, which can induce cell proliferation and survival, has been well correlated with the growth effect of E2 on breast cancer cells." (PMID 21695171, 2011). "This review aims to coalesce several papers across the spectrum of this research to tie together molecular pathways and illustrate emerging trends to help direct future research into CXCR4 as a prognostic and/or predictive marker for breast cancer." (PMID 22295222, 2011). "This study provides novel insights about anti-tumorigenic effects of CB2 receptors in breast cancer through modulation of CXCR4/CXCL12 signaling axis." (PMID 21915267, 2011). "CXCL12 is the ligand for CXCR4 and is highly expressed in areas common for breast cancer metastasis, including the axillary lymph nodes." (PMID 22295222, 2011). "For example, plumbagin was found to suppress CXCR4 expression in HER2 overexpressing BT474 breast cancer cells." (PMID 21880153, 2011).
breast carcinoma (continued). "Perhaps as in the case of pancreatic cancer (where the CD133+CXCR4+ cell population is responsible for metastasis), it is the CXCR4-positive SP population of breast cancer cells that are responsible for breast cancer metastasis." (PMID 24212798, 2011). "To elucidate the role of CB2 and CXCR4 in breast cancer, we assessed their expression in tumor samples from 82 breast cancer patients using tissue microarrays." (PMID 21915267, 2011). "While this pathway was worked out on cell lines for chondrosarcoma, HIF-1α increases in hypoxic conditions have also been shown to upregulate CXCR4 in carcinoma of the breast." (PMID 22295222, 2011). "The SDF-1α/CXCR4 attraction leads breast cancer cells to leave the circulation and migrate into organs that express large amounts of chemokines, where the cancer cells proliferate, induce angiogenesis and form metastatic tumors." (PMID 21880153, 2011). "Regarding breast cancer cells, CXCR4 was also proposed to be induced by E2 but only through post-translational effects in a particular model of MCF-7 cells overexpressing HER2." (PMID 21695171, 2011). "CXCL12/CXCR4 signaling has been shown to stimulate the chemotactic and invasive behavior of breast cancer cells in vitro and in vivo, and has been proposed to serve as a homing mechanism for cancer cells to sites of metastasis." (PMID 22152016, 2011). "CXCR4 is expressed in several human cancers including glioma, neuroblastoma, pancreatic and breast, with overexpression of CXCR4 in breast cancer correlating with poor patient prognosis." (PMID 22152016, 2011). "The location of CXCR4 staining was studied in breast cancer tissue samples, benign tissue samples that were adjacent to tumor tissue, and atypical hyperplasia samples." (PMID 22295222, 2011). "The majority of breast cancers have been shown to overexpress chemokine receptor CXCR4, which has been correlated with poor prognosis." (PMID 21915267, 2011). "CXCR4 is an important factor in the migration, invasiveness and proliferation of breast cancer cells and silencing of CXCR4 blocks breast metastasis." (PMID 22053985, 2011). "Previous studies have reported that both CXCR4 and CXCR7 play roles in breast cancer growth and metastasis, with both receptors being implicated in primary tumor growth, invasion and metastasis formation." (PMID 22152016, 2011). "Several studies using gene silencing strategies to reduce CXCR4 expression have demonstrated that this results in impaired invasion of breast cancer cells in vitro and inhibits breast cancer metastasis in vivo." (PMID 24212798, 2011). "A litany of studies have emerged in the last five years examining CXCR4 and axillary lymph nodes, covering multiple approaches of how CXCR4 in the setting of axillary lymph nodes can impact our understanding of breast cancer." (PMID 22295222, 2011). "CXCL12 is expressed at high levels in the bone marrow, lung, liver, and lymph nodes, common sites of breast cancer metastasis, with protein extracts from these organs stimulating chemotaxis of breast cancer cells in a CXCR4-dependent manner." (PMID 22152016, 2011). "In breast cancer, CXCR4 signaling was shown to play a crucial role in distant recurrence by mediating actin polymerisation and pseudopodia formation, thus, leading to chemotactic and invasive responses." (PMID 21349176, 2011). "After creating an “expression score” to quantify CXCR4 expression in their breast cancer and lymph node specimens, this group was able to show that primary breast cancer specimens exhibited a higher score than lymph node metastases (P < 0.001)." (PMID 22295222, 2011). "Recently, Luker and colleagues successfully utilized this approach to image activation and inhibition of chemokine receptor CXCR4 signaling in breast cancer metastasis in vivo by detecting interactions between CXCR4 and β-arrestin." (PMID 22346573, 2011).